IL1B (interleukin 1 beta)
Diseases named in the same sentence as IL1B in open-access papers (continued):
Sharing a sentence is not in itself a finding about the gene and the disease.
Listeria infection (19 papers, 2015 to 2025). "Previous work has demonstrated that Ch25h-deficient macrophages overproduce IL-1β and have deregulated caspase-1-activating inflammasome activity in response to Listeria monocytogenes infection or LPS stimulation." (PMID 36831236, 2023). "Previously, extracts from S. miltiorrhiza have shown immune regulatory effects on Listeria infection in Balb/c mice by decreasing serum IgE levels and IL-1β and by increasing natural killer (NK) cells, macrophages, and peripheral lymphocytes." (PMID 34691223, 2021). "Conversely, in the miR‐146a KO mouse model, a cell‐intrinsic increased frequency of double‐producing IL‐17+ IFNγ+ cells was observed among γδ27− T cells in vitro (stimulated with IL‐1β and IL‐23) and in vivo, upon Listeria monocytogenes infection." (PMID 33191519, 2020). "Listeriolysin, originally suggested to play a role in IL-1β responses during Listeria infection via pore formation, directly activates the inflammasome by K+ efflux induction." (PMID 26617605, 2015). "T‐bet deficiency was found to significantly reduce IFNγ expression by peripheral γδ27+ T cells both in vitro and in vivo upon infection with murid herpes viruses, while also impairing IFNγ production by γδ27−CCR6+ T cells stimulated with IL‐1β or IL‐23 in vitro or during Listeria infection in vivo." (PMID 33191519, 2020). "Although we observed less IL-1β production in Tlr2−/− than Clec5a−/− macrophages incubated with L. monocytogenes, Tlr2−/− mice were more resistant than Clec5a−/− mice to Listeria infection." (PMID 28824166, 2017). "Listeria infection represses the constitutive expression of APP genes in hepatocytes and, importantly, this repression is maintained under conditions of inflammation, after stimulation with the pro-inflammatory cytokines IL-6 and IL-1β." (PMID 34858876, 2021). "The repeated inhalation of such particles not only suppressed alveolar macrophages and T cell-mediated immune response to induced Listeria infection in rats, but also suppressed the in vitro production of IFN-γ, TNF-α, IL-1β and IL-6 by peripheral blood monocytes from healthy individuals." (PMID 26588473, 2015). "Therefore, these compounds could be considered for use as a potential treatment for listeriosis by inhibiting proteins such as, IL2, MAPK1, SRC, EGFR, PTPRC, TNF, IL1B, and ERBB2." (PMID 36671206, 2022). "In addition, IL-1β has been shown to drive a polyfunctional non-classical Th1-type response in the context of Listeria monocytogenes infection." (PMID 32793237, 2020).
malnutrition (19 papers, 2019 to 2025). Inadequate nutrition resulting from poor diet, malabsorption, or abnormal nutrient distribution. "Under malnutrition conditions, they reported decreased mRNA expression of genes associated with regeneration and mesenchymal stem cell accumulation, along with an increase in myeloperoxidase and IL-1β mRNA expression." (PMID 40077629, 2025). "The CC genotype of IL1B gene was characterized with 56.2% sensitivity and 48.2% specificity in the prediction of malnutrition (AUC = 0.52; p = 0.6894)." (PMID 38610941, 2024). "The expression of Il1b and Tnf following LPS challenge was amplified in malnourished mice, whereas malnutrition blunted LPS-induced Il6 expression." (PMID 35983045, 2022). "Depletion of inflammatory monocytes by administration of DT to malnourished mice reduced bone marrow expression of caspase-1, and Il-1β in LPS challenged mice confirming their role in malnutrition-related inflammasome activation." (PMID 35983045, 2022). "Conversely, THI patients with low levels of cytokines had lower risk of malnutrition during their stay in the ICU, IL-10 and TNFα (p < 0.001 to 0.01), IL-6 and IL-1β (p 0.23 to 0.900)." (PMID 31443251, 2019). "The assessment of IL1B SNP and IL-1β plasma concentration demonstrated a nonsignificant diagnostic usefulness in the prediction of malnutrition." (PMID 38610941, 2024). "Based on the CONUT score, the prevalence of patients with moderate/severe malnutrition risk (score ≥ 5) was 10%, showing lower age, body mass index and fat mass, but higher IL-6 and IL-1β levels than subjects classified as not at risk (score 0–1)." (PMID 37111172, 2023). "Malnutrition promotes the phenotypic transformation of immune cells to pro-inflammatory phenotypes, secreting pro-inflammatory cytokines such as IL-1β, IL-6, IL-8, TNF-α, and IL-2, while anti-inflammatory cytokines such as IL-1 receptor antagonists, IL-4, IL-10, and IL-13 decrease." (PMID 35003070, 2021). "Pro-inflammatory cytokines, including IL-6, IL-1β, and TNF-α, are released, activating pathways contributing to malnutrition development." (PMID 40507748, 2025). "Malnutrition can induce a low-grade systemic inflammatory response with elevated serum levels of TNF, IL-1β, and IL-6." (PMID 38651412, 2024). "The release of proinflammatory cytokines, such as IL-6, IL-1β, and TNF-α, is determinant of the pathophysiology of malnutrition." (PMID 39683535, 2024). "To examine the impact of malnutrition on other pro-inflammatory cytokines in T2DM, we measured the circulating levels of pro-inflammatory cytokines (G-CSF, GM-CSF, MCP-1, MIP-1β, IL-6, IL-7, IL-8, IL-12p70 and IL-1β) in LBMI and NBMI individuals." (PMID 33183277, 2020).
polycystic ovary syndrome (19 papers, 2015 to 2026). A disorder that manifests as multiple cysts on the ovaries. "SGD has demonstrated anti-inflammatory effects in other models, including reduction of IL-1β and IL-6 in polycystic ovary syndrome." (PMID 41446282, 2025). "In line with mouse data, hyperandrogenemia also increases levels of IL-1β, IL-8, and IL-18 in PCOS patients." (PMID 39911236, 2024). "The pro-inflammatory Interleukin 1β (IL-1β) contributes to LOX overexpression in polycystic ovary syndrome (PCOS), with increased LOX and IL-1β levels being observed in granulosa cells and follicular fluid of PCOS patients." (PMID 32708046, 2020). "Studies have indicated that individuals with polycystic ovary syndrome exhibit elevated levels of inflammatory markers such as TNF, IL-6, CRP, IL-18, IL-1β, and white blood cell counts." (PMID 40933264, 2025). "Coptis chinensis, an important medicinal plant in the Ranunculaceae family, has been found to reverse the pathological damage of ovarian tissue in polycystic ovary syndrome and regulate the mRNA and protein expression levels of MAPK1, CXCL8, IL-6 and IL-1β." (PMID 40842497, 2025). "Postnatal overfeeding stimulated JNK1 activation independent of hyperandrogenemia; nevertheless, the synergistic effect of both factors triggered NLRP3 activation and increased IL1β expression in the small litter DHT-treated group." (PMID 39268230, 2024). "Rimonabant treatment for 12 weeks in obese women with polycystic ovarian syndrome resulted in increased circulating levels of VEGF however, the treatment did not alter TNF-α, IL-1β, IL-2, and IL-6, which is in contrast to our results following AM251 treatment." (PMID 36232744, 2022).
prion disease (19 papers, 2010 to 2026). A transmissible disease that is caused by a protein that is able to induce abnormal folding of normal cellular proteins, leading to characteristic spongiform brain changes, which are associated with neuronal loss without an inflammatory response. "Furthermore, the inflammatory cytokine IL-1β has been shown to be an important factor in prion disease-associated inflammation." (PMID 22531291, 2012). "AD pathways involve (IL6, AKT1 and IL1B); prion disease involves (IL6 and IL1B); and pathways of neurodegeneration-multiple diseases involve (IL6, AKT1 and IL1B)." (PMID 41601963, 2026). "A second pathway implicated in in vitro models of prion disease is the Nod-Like Receptor Protein 3 (NLRP3) inflammasome, reported as the primary source of microglia-derived IL1β in prion infection." (PMID 36581683, 2022). "We found that these transcripts are either unchanged (Nlrp3 and Il1b) or only moderately upregulated (Pycard and, to a less extent, Casp1) in the latest stages of prion disease with respect to baseline levels." (PMID 25671600, 2015). "This controversial state of affairs motivated us to investigate the contribution of NLRP3/ASC inflammasomes to brain levels of IL-1β in our experimental model of prion disease." (PMID 25671600, 2015). "Both genotypes showed histologic features characteristic of prion disease, accumulation of partially PK-resistant PrP and similar levels of IL-1β in the brain." (PMID 25671600, 2015). "Firstly, we looked at levels of cytokines/chemokines known to be induced in prion disease (Cxcl10, Il-12b and Il-1b)." (PMID 24655482, 2014). "The only in vivo data derives from a model of prion disease, where phagocytic microglia have been qualitatively observed not to express the pro-inflammatory cytokine interleukin 1beta (IL-1β)." (PMID 23386811, 2013). "Nonetheless, one study was unable to detect secretion of IL-1β in mice with prion disease." (PMID 35163653, 2022). "Collectively, these data indicate that transcriptional mechanisms could be of relevance for the release of IL-1β during prion disease." (PMID 25671600, 2015). "Based on these studies, it was postulated that pharmacological interference with the NLRP3 inflammasome/IL-1β signaling pathway could be beneficial against prion diseases." (PMID 25671600, 2015). "The upregulation of pro-inflammatory cytokines like IL-1-β and TNF-α occurs as prion diseases progress." (PMID 40498027, 2025). "Using the ME7 model of prion disease and systemic challenge with poly I:C (12 mg/kg i.p.)we have shown an amplified expression of IFN-α and β and of the pro-inflammatory genes IL-1β and IL-6." (PMID 20399848, 2010). "This is consistent with data showing that CNS prion disease is unaltered in the steady state in mice lacking the NLRP3 inflammasome (essential for release of IL-1β), NF-κB signalling or MyD88 signalling." (PMID 33023255, 2020). "Several studies have suggested that the up-regulation of TNFα, IL1β, IL6, and COX2 plays important roles in many inflammatory diseases including cytotoxicity in brain injuries and many neurodegenerative diseases such as AD, PD, and prion diseases." (PMID 32560481, 2020). "Here, IFNAR1 deficiency did not impact upon Il1b mRNA levels and decreased Il10 and Trem2 expression suggesting that canonical IFNAR‐STAT1/2 signaling is dominant in ME7 prion disease." (PMID 30680794, 2019). "Although interleukin (IL)-1β release by prion-induced microglia has been widely reported, the mechanism by which primed microglia become activated and secrete IL-1β in prion diseases has not yet been elucidated." (PMID 22531291, 2012). "The effects of systemic LPS treatment on CNS prion disease coincide with the enhanced abundance and inflammatory activation of the microglia, as well as elevated production of the pro-inflammatory cytokines TNF-α, IL-1β and IL-6, and cytotoxic mediators such as nitric oxide." (PMID 33023255, 2020).
prion disease (continued). "The source of this increase in IL-1β during prion diseases has not been elucidated." (PMID 25671600, 2015). "Because pro-IL-1β is not constitutively expressed in microglia, the cells were primed with 300 ng/ml LPS for 3 hours to induce pro-IL-1β synthesis and to mimic the chronic activation of microglia in prion disease." (PMID 22531291, 2012).
squamous cell carcinoma (19 papers, 2006 to 2025). A carcinoma arising from squamous epithelial cells. "Some studies have shown that IL-1β mRNA and protein levels are greater in patients with gastric esophageal carcinoma and squamous cell carcinoma than in controls." (PMID 40244135, 2025). "Adenocarcinomas were more frequent in Q1 (lowest IL-1β expression) than Q4 (72.2% vs. 44.3%, p < 0.001), while squamous cell carcinomas (SCCs) were more common in Q4 (12.1% vs. 36.4%, p < 0.001)." (PMID 40940992, 2025). "It has been reported that SCLC (Small cell lung cancer) and SLC (Squamous cell carcinoma) patient tissues have higher IL-1β expression than normal tissues." (PMID 38188678, 2023). "IL-1β had an association only with adenocarcinoma, while IFN-γ had an association only with squamous-cell carcinoma." (PMID 38067398, 2023). "IL-1β had an association only with small-cell carcinoma (HR [95% CI]: 1.17 [1.03–1.33], while IFN-γ had an association only with squamous-cell carcinoma (HR [95% CI]: 1.18 [1.04–1.34])." (PMID 38067398, 2023). "Tgfbr1 and Pten were able to inhibit the expression of NLRP3, ASC, caspase-1, IL-1β, and IL-18 in a mouse squamous cell carcinoma of the head and neck model." (PMID 32723297, 2020). "EGF also induced IL-1β gene expression in squamous carcinoma cells, such as SCC4, SCC25, TU183, and CA922." (PMID 23383347, 2013). "Differential manipulation of IL-1β by EGF in squamous cell carcinomas can offer new methods for targeting IL-1 in cancer therapy." (PMID 23383347, 2013). "However, a recent study reported significantly higher IL-1β protein levels in gastroesophageal cancer and squamous cell carcinoma." (PMID 39766795, 2024). "IL-1β and IFN-γ had associations with adenocarcinoma and squamous-cell carcinoma, respectively." (PMID 38067398, 2023). "However, expression of M1 markers was decreased in patients with adenocarcinoma and squamous carcinoma; serum levels of interleukin 1 beta (IL-1β), interleukin 4 (IL-4), IL-6, and IL-8 were higher in patients with large-cell carcinoma than in healthy controls." (PMID 34834295, 2021). "For instance, IL-1β is a marker of intraepithelial lesions in young women, and CXCL10 expression is a predictor of squamous cell carcinoma across all age groups." (PMID 38891028, 2024). "In the squamous cell carcinoma, the expression of Nanog (P = 0.005), SOX2 (P = 0.002), and OCT4 (P = 0.008) was significantly increased after IL-1β stimulation." (PMID 32547321, 2020). "In our study, we found that the IL-1β gene and protein expression were induced by EGF in squamous cell carcinoma." (PMID 23383347, 2013). "Meanwhile, IL-1β could upregulate the expression of CXCR4 and promote the metastasis of squamous cell carcinoma." (PMID 32724311, 2020). "However, IL-1β may be a specific biomarker for small-cell carcinoma, and IFN-γ may be a biomarker for squamous-cell carcinoma." (PMID 38067398, 2023). "Squamous cell carcinoma SCC7 stimulated with or without IL-1β were inoculated subcutaneously." (PMID 32547321, 2020).
abdominal aortic aneurysm (18 papers, 2015 to 2026). Enlargement and ballooning of the vessel that supplies arterial blood to the abdomen, pelvis and legs. "Similarly, in the context of Trem-1−/− with angiotensin-II induced abdominal aortic aneurysm, inflammation and aortic wall degradation were markedly reduced, which was associated with decreased expression of Il1b, TNF-α, MMP2, and MMP9." (PMID 41226426, 2025). "Thoracic and abdominal aortic aneurysms differ in terms of etiology, the cellular origin of IL-1β, and their degree of inflammation dependence, suggesting that IL-1β-related mechanisms are disease-specific." (PMID 42292365, 2026). "Previous studies have shown that IL-1B-induced NETs formation can promote experimental abdominal aortic aneurysm." (PMID 40620701, 2025). "Our data indicate that IL-1β expression in the AAA wall is increased in patients with multiple arterial aneurysms compared to that in patients with a single abdominal aortic aneurysm." (PMID 37238981, 2023). "It has been demonstrated that IL1B triggers the activation of aortic infiltrated neutrophils and further leads to the formation of abdominal aortic aneurysms in an experimental murine model." (PMID 36159873, 2022). "Recent studies have also confirmed its role in abdominal aortic aneurysms, Here, we demonstrated the role of IL-6 and IL-1B in TAAA disease." (PMID 34202072, 2021). "A study has shown that neutrophil extracellular traps induced by IL1B play a major role in the formation of abdominal aortic aneurysms." (PMID 33511216, 2021). "For instance, IL-1β have been shown to be co-localized with NETs in the detected human abdominal aortic aneurysms (AAAs) and in vitro tests have revealed that IL-1β induces the formation of NETs which is specifically inhibited by IL-1RA." (PMID 32228650, 2020). "Here, the authors report that IL-1β localizes within NETs in mice with experimental abdominal aortic aneurysms and that IL-1β blockade inhibits NETosis in isolated neutrophils." (PMID 31779200, 2019). "Additionally, high infiltration of IL-1B-positive macrophages was observed in abdominal aortic aneurysms." (PMID 39118044, 2024). "We obtained six macrophage hub genes (IL-1B, CXCL1, SOCS3, SLC2A3, G0S2, and CCL3) that can effectively diagnose abdominal aortic aneurysm." (PMID 38867262, 2024). "In addition, a recent study noted that knockdown of PVT1 decreased levels of MMP-2 and MMP-9, augmented TIMP-1 expression, and suppressed serum levels of TNF-α, IL-1β, and IL-6 in VAMC and ApoE-/- mice of abdominal aortic aneurysm model." (PMID 34775377, 2021).